MT1M (metallothionein 1M)
Description:
Metallothioneins have a high content of cysteine residues that bind various heavy metals; these proteins are transcriptionally regulated by both heavy metals and glucocorticoids.
Synonyms: MT-1M; MT-IM; MT1K; MT1
Tractability: No criterion of Open Targets' tractability assessment is met for any kind of drug.
Gene: Protein-coding gene on chromosome 16 (56,632,562 to 56,633,981, forward strand). Ensembl gene ENSG00000205364.
Pathways (Reactome):
Cellular responses to stimuli: Metallothioneins bind metals
Gene Ontology:
Molecular function: protein binding; metal ion binding; zinc ion binding
Biological process: cellular response to cadmium ion; cellular response to copper ion; cellular response to zinc ion; detoxification of copper ion; intracellular zinc ion homeostasis; negative regulation of growth
Cellular component: cytoplasm; nucleus
Genetic constraint (gnomAD): Loss-of-function variants: 12 observed, 9.25 expected, observed/expected ratio (o/e) 1.3, 90% interval 0.82 to 1.87. That is too few expected variants to judge how well the gene tolerates losing a copy. Missense variants: 84 observed, 77.45 expected, observed/expected ratio (o/e) 1.08, 90% interval 0.91 to 1.3. Synonymous variants: 28 observed, 31.09 expected, observed/expected ratio (o/e) 0.9, 90% interval 0.67 to 1.24.
Homologues: Orthologues: chimpanzee MT1G (80% identical), zebrafish mt2 (59% identical). Paralogues in human: MT1B (85% identical), MT1A (82% identical), MT1F (82% identical), MT1G (82% identical), MT1X (82% identical), MT1H (80% identical), MT2A (80% identical), MT1HL1 (77% identical), MT3 (67% identical), MT4 (56% identical), MT1E (48% identical).
Diseases named in the same sentence as MT1M in open-access papers:
MT1M is named in the same sentence as 37 diseases in open-access papers, as found by Europe PMC text mining. Sharing a sentence is not in itself a finding about the gene and the disease. The quoted sentences say what the papers report.
hepatocellular carcinoma (14 papers, 2013 to 2025). A malignant tumor that arises from hepatocytes. "MT1M encodes a metallothionein protein that functions as a tumor suppressor by downregulating the NF-kB pathway activity and subsequent proliferation in hepatocellular carcinoma." (PMID 38751776, 2024). "Previous studies have indicated that MT1E, MT1F and MT1M are antitumor genes in malignant melanoma, colon carcinoma cells, and hepatocellular carcinoma HepB3, respectively." (PMID 36009228, 2022). "In hepatocellular carcinoma, the low expression of MT1M is positively correlated with poor prognosis, suggesting that MT1M plays a tumor-suppressive role in hepatocellular carcinoma." (PMID 34336838, 2021). "For example, miR-545-3p targeted MT1M to facilitate the progression of human hepatocellular carcinoma." (PMID 33053117, 2020). "A methylation profiling analysis indicated that the MT1M promoter is methylated in the majority of hepatocellular carcinoma tumors examined." (PMID 23502468, 2013). "In another study, low MT1M expression was found to be linked to high alpha-fetoprotein (AFP) levels and high tumor recurrence rates following curative resection in patients with hepatocellular carcinoma." (PMID 30139373, 2018). "In addition, combined MT1M and MT1G promoter methylation in hepatocellular carcinoma patients was associated with a high incidence of vascular invasion and lymph node or extrahepatic metastasis, thereby acting as an effective prognostic marker." (PMID 30139373, 2018). "Moreover, restored expression of MT1M in the hepatocellular carcinoma cell line, Hep3B, which lacks endogenous MT1M expression, suppressed cell growth in vitro and in vivo and augmented apoptosis induced by tumor necrosis factor." (PMID 23502468, 2013). "In hepatocellular carcinoma (HCC), miR-24-3p is significantly upregulated and decreases metallothionein 1M expression to promote the initiation and progression of HCC." (PMID 36814556, 2023). "However, MT1M expression markedly decreased in human hepatocellular carcinoma specimens." (PMID 23502468, 2013). "Furthermore, stable expression of the new functional member of MT1, MT1m, blocked TNF-α-induced degradation of IkBα and transactivation of NF-κB in human hepatocellular carcinoma." (PMID 34804020, 2021). "In present study, it was found that MT1M was downregulated in more than 77.1% (91/118) of hepatocellular carcinoma (HCC) tissues compared with adjacent non-tumor tissues." (PMID 28380433, 2017). "In hepatocellular carcinoma (HCC), silencing of tumor suppressor genes such as HHIP, MT1M, PZP, and TTC36 is a key driver of carcinogenesis." (PMID 41335282, 2025).
gastric cancer (6 papers, 2019 to 2025). A primary or metastatic malignant neoplasm involving the stomach. "MT1M suppression is known to promote cell growth and stemness properties in gastric cancer cell lines through increased GLI1 expression." (PMID 38751776, 2024). "Overexpression of MT1M inhibited the proliferation, migration, and invasion of gastric cancer cells and promoted apoptosis of gastric cancer cells." (PMID 39061894, 2024). "Meanwhile, MT1M may also play an anti-cancer role by decreasing the stemness of gastric cancer cells and increasing their sensitivity to 5-fluorouracil." (PMID 39061894, 2024). "For RFS, high expression of OLFML2B, MT1M, and SIDT2 indicated a poor RFS of patients with GC, whereas gastric cancer patients with higher expression of CYP4X1 possessed better RFS from TCGA cohort." (PMID 36092901, 2022). "Methylation inactivation in tumor suppressors genes, such as MT1M, MT1H, MT1X, and HRK, is responsible for the development of various cancers, such as prostate cancer, liver cancer, colorectal cancer, and gastric cancer, but loss of these genes may be linked with the pathogenesis of BRCA." (PMID 31311202, 2019). "Notably, DNA methylation of some MT isoforms in gastric cancer, like MT1A, MT1B, MT1H, MT1M, MT3, and MT4, was higher than their paired normal tissue except remaining isoforms." (PMID 31380415, 2019).
liver cancer (3 papers, 2019 to 2023). An epithelial or non-epithelial malignant neoplasm that arises from the liver. "These analyses demonstrated that HHIP was a key TSG controlling liver cancer cell proliferation and cell viability; in fact, only modest changes in cell viability were achieved when individually targeting MT1M, PZP, and TTC36." (PMID 37120619, 2023). "Our analysis disclosed that MT1E was downregulated in liver cancer and may serve a similar function as MT1M." (PMID 34423049, 2021).
prostate carcinoma (3 papers, 2019 to 2025). A carcinoma that arises from epithelial cells of the prostate gland. "MT1M loss was a top ProstaMine hit in both NKX3-1-loss and RB1-loss prostate cancer and has not been reported as a factor involved in PCa progression." (PMID 38751776, 2024).
esophageal cancer (2 papers, 2023 to 2024). A primary or metastatic malignant neoplasm involving the esophagus.
glioma (2 papers, 2018 to 2023). A benign or malignant brain and spinal cord tumor that arises from glial cells (astrocytes, oligodendrocytes, ependymal cells). "It is important to pinpoint that among the oncogenes upregulated in the S group, we identified the MT1M gene, which has been already reported associated to a more aggressive glioma behavior." (PMID 29844869, 2018).
periodontal disease (2 papers, 2019 to 2022). "The present validation study confirmed that the genes for the MT1F, MT1X, MT1M, MT1E, and MT2A isoforms exhibit a statistically significant alteration of expression in Down’s syndrome patients with active periodontal disease and implant failure." (PMID 35741790, 2022).
asthma (1 paper, 2015). "Others have been associated with diabetes (ZBED3), asthma (EMID2), and cancer (FBXO3, HOOK2, MT2A, EIF3E, RPH3AL, PTRF, MT1M, STK32A)." (PMID 25748564, 2015).
breast carcinoma (1 paper, 2015). "Cell proliferation and invasion assays suggested MT1F and MT1M may have anti-oncogenic roles in breast cancer." (PMID 25763113, 2015). "Cell proliferation and invasion assays suggested MT1F and MT1M may play an anti-oncogenic role in breast cancer." (PMID 25763113, 2015).
glioblastoma (1 paper, 2018). The most malignant astrocytic tumor (WHO grade IV). "The MT1M gene has been described in the literature as associated with poor survival in glioblastoma." (PMID 29844869, 2018). "In the rest of the amplified genes, resulted by CNV analysis, we identified two gene families involved in glioblastoma such as MT1M and GPR56." (PMID 29844869, 2018).
lung adenocarcinoma (1 paper, 2023). A carcinoma that arises from the lung and is characterized by the presence of malignant glandular epithelial cells. "While in lung adenocarcinoma MT1M overexpression was also found to inhibit A549 cell viability and migration ability, decreased MT1M expression promoted tumor cell proliferation and migration." (PMID 37259059, 2023).
radiation-induced brain injury (1 paper, 2025). An injury to the brain which results results from exposure to radiation. "In this study, we systematically identified 35 differentially expressed proteins, including PHLDA3 and MT1M, using a rat model of radiation-induced brain injury, coupled with TMT-tagged quantitative proteomics and high-resolution mass spectrometry." (PMID 41289299, 2025).
thyroid cancer (1 paper, 2023). "In vitro experiments showed that MT1M upregulation significantly inhibited colony formation, proliferation, migration, and invasion of thyroid cancer (PTC) cell lines, it is suggested that MT1M may be a potential new marker and target for thyroid cancer therapy." (PMID 37259059, 2023).
tumor (26 papers, 2014 to 2025). "Reduced gene expression of GSTO2, SMAD4, and MT1M was also significantly associated with high-grade tumor histology (Gleason grade group ≥ 8) in NKX3-1-loss tumors." (PMID 38751776, 2024). "The MT1M gene was selected because it is highly methylated in ERα + cells and has been implicated as a tumor suppressor in earlier studies, while the selection of MT1F is because it is most highly expressed in MCF7 cells compared to other cell lines." (PMID 25763113, 2015). "It was indicated that MT1M might be associated with tumor differentiation and immunostaining of MT1M might be usefulness to HCC diagnosis." (PMID 28380433, 2017). "Metallothionein 1 M (MT1M) plays a key role in tumor progression and formation, and its expression is positively correlated with clinical prognosis." (PMID 40052129, 2025). "Consistent with these previous findings, we found that TERT and THBS4 had significantly higher expression levels in tumor than in normal matched samples in all cohorts and that MT1M showed the opposite tendency." (PMID 38985879, 2024). "Subsequently, metallothionein-1 M (MT1M), which was previously identified as a tumor suppressor, is targeted by miR-545-3p and is thus downregulated in ESCC tissues and cells, leading to resistance to cisplatin." (PMID 38540273, 2024). "We used qRT-PCR to measure the relative mRNA expression levels of four risk genes (TIPARP, SERPINA3, MT1M, and CST2) in the normal prostate tissue cell RWPE-1 and in different tumor cell states such as LNCaP and C4-2 cell lines." (PMID 37346077, 2023). "It was also reported that the MT1M isoform has a tumor suppressive function in ESCC cell lines in vitro." (PMID 34572779, 2021). "14-3-3ε overexpression significantly induced tumor growth in nude mice, and this effect was abrogated by MT-1M overexpression." (PMID 31138789, 2019). "Downregulation of MT1M in HCC tumor tissues was reported well, however, the mechanism of MT1M effect needs further verification by multi-groups, and the application of MT1M as HCC biomarker for clinical diagnosis needs evaluation." (PMID 28380433, 2017). "The expression level of MT1M reverse correlates with tumor differentiation in HCC (r = −0.836, P < 0.01)." (PMID 28380433, 2017). "Thus, MT1M expression might be associated with the tumor cell differentiation." (PMID 28380433, 2017). "In conclusion, it were found that: 1) downregulated MT1M in HCC tumors was a potential tumor marker; 2) MT1M suppressed HCC tumorigenesis possibly by inducing cell cycle arrest, enhancing apoptosis and inhibiting cell migration and invasion." (PMID 28380433, 2017). "Similarly, MT1M also showed a tumor-suppressive ability to suppress cell viability, migration, and invasion and activate apoptosis in vitro." (PMID 35300417, 2022). "Some other isoforms of MT1 were identified as tumor suppressors such as MT1M and MT1H in HCC32,38." (PMID 31732712, 2019). "However, MT1M expression was moderate or strong (score 2~3) in most non-tumor tissues (106 of 118 cases)." (PMID 28380433, 2017). "In conclusion, MT1M was identified as a potential tumor marker for HCC and may serve as a useful therapeutic agent for HCC gene therapy." (PMID 28380433, 2017). "GSTO2 and MT1M have been described as tumor suppressors in cancer, and SMAD4 is listed as a tumor suppressor gene in the COSMIC Cancer Gene Census." (PMID 38751776, 2024). "Our results showed that the relative mRNA expression of ADIRF, MT2A, MT1M, and JUNB was downregulated after TGF-beta treatment and/or tumor stimulation, while the expression level of C11orf96 was upregulated, even after tumor stimulation." (PMID 33777046, 2021). "Moreover, overexpression of MT-1M could reduce cell proliferation and tumor growth in HCC7." (PMID 31138789, 2019). "Four genes from the metallothionein cluster on human chromosome 16q13 (MT1A, MT1E, MT1M, MT2A) were overexpressed in 231_HM.LNm5 tumours only, thus placing them in the metastatic virulence category." (PMID 29720474, 2018).
tumor (continued). "Interesting, 3 MT superfamily numbers, MT1M, MT1G and MT1P2 were significantly down-regulated in the HCC tumor tissues." (PMID 28380433, 2017). "GSTO2 and MT1M functions have not been reported as factors in PCa progression, whereas loss of SMAD4 function has been shown to drive tumor growth and metastasis." (PMID 38751776, 2024). "At the same time, tumor-suppressive genes such as MT1G, MT1M, CDKN1C, and DCN were overexpressed." (PMID 30568916, 2018). "As the representative results, MT1M was strong stained in the cytoplasm of non-tumor cells, but in tumor cells, staining was weak or negative." (PMID 28380433, 2017). "Furthermore, overexpression of MT1M inhibited cell viability, colony formation, cell migration and invasion in HCC cell lines and tumor cell growth in xenograft nude mice, and activated cell apoptosis in HCC cell lines." (PMID 28380433, 2017). "In addition, immunohistochemistry analysis showed MT1M was negative or weak staining in tumor tissues but moderate or strong staining in adjacent non-tumor tissues." (PMID 28380433, 2017). "Furthermore, MT1M expression was weak or negative in most HCC tumor tissues (90 of 118 cases)." (PMID 28380433, 2017). "But, the OS of MT1M was not statistically significant, while the OS of TNFAIP6 and SIDT2 were not in accordance with expression levels in tumor tissues." (PMID 36092901, 2022).
cancer (15 papers, 2015 to 2025). A tumor composed of atypical neoplastic, often pleomorphic cells that invade other tissues. "The change of genus Prevotella 2 abundance was also associated with the reduced expression of MT1M in cancer tissues compared with healthy tissues." (PMID 32321427, 2020). "In addition, metallothionein (MT) family proteins, such as MT-2A, are highly expressed in cancer-associated fibroblasts, and the methylation of MT-1 genes (MT-1A, MT-1M, and others) is significantly higher in ESCC samples than that in normal esophageal mucosa tissue." (PMID 37840147, 2023). "MT1M, SLCO1B3, SPINK1, and AKR1B10 were cancer-related genes that were associated with different human diseases, especially in HCC." (PMID 36246599, 2022). "Several metallothionein genes, including MT1E, MT1G and MT1M were upregulated in the SPINK1 general cancer pathway." (PMID 35369880, 2022). "Strikingly, members of the metallothionein family, including MT1M, MT1H, MT1G, MT1F, MT1E, MT1X, and MT1A, were significantly downregulated in cancer cells." (PMID 35967424, 2022). "While down-regulated genes were associated with GO categories such as cellular response to zinc ion where members of metallothionein family (MT1M, MT1H, MT1X, MT1G, and MT1F) play important roles in carcinogenesis of various cancer types." (PMID 32849813, 2020). "Recently, MT1 isoforms, in particular MT1M and MT1G, were suggested as possible biomarkers for HCC and other human cancers." (PMID 33585212, 2020).
MT1M also shares sentences with these, for which no sentence is quoted: colon carcinoma (3 papers); esophageal squamous cell carcinoma (3); colorectal cancer (2); Alzheimer disease (1); amyloidosis (1); atherosclerosis (1); chronic hepatitis B (1); COVID-19 (1); dermatomyositis (1); diabetes (1); Down syndrome (1); endometriosis (1); infection (1); lung carcinoma (1); malignant melanoma (1); metabolic dysfunction-associated steatohepatitis (1); metabolic dysfunction-associated steatotic liver disease (1); neuroblastoma (1); nutritional deficiency (1); ovarian carcinoma (1); poisoning (1); steatosis (1).